INS (insulin)
Diseases named in the same sentence as INS in open-access papers (continued):
Sharing a sentence is not in itself a finding about the gene and the disease.
Insulin resistance (continued). "Identification of circulating miRNAs connected with insulin resistance would have the potential to offer innovative methods of assessing insulin sensitivity to detect prediabetes and provide further evidence about the underlying molecular mechanisms connected to insulin impairment." (PMID 34243726, 2021). "In T2DM patients with insulin resistance, the regulation of insulin on HGP is defective." (PMID 34582711, 2021). "Disruption of insulin signalling due to insulin resistance makes neurons more vulnerable to metabolic insults and may contribute to the development of DN77." (PMID 33436718, 2021). "Therefore, in type-2 diabetic individuals, insulin increases in the bloodstream, due to insulin resistance, which in turn increases the LDL-C particles thereby increasing the LDL-C levels." (PMID 34162950, 2021). "Insulin sensitivity is frequently assessed on the basis of the ratio between fasting insulin and glucose levels calculated as the homeostatic model assessment for insulin resistance (HOMA-IR) index." (PMID 34106350, 2021). "Caveolin-1 knockout mice develop remarkable insulin resistance, while upregulation of caveolin-1 could enhance insulin signal transduction and therefore improve glucose uptake after insulin stimulation." (PMID 34917687, 2021). "In addition to the change in FBG and the serum insulin level, we found that the insulin resistance of the SG group was significantly improved compared with that of the SHAM group as assessed by HOMA-IR." (PMID 34858216, 2021). "The insulin resistance associated with pregnancy is accommodated by an expansion of pancreatic β-cell mass (BCM) and increased insulin secretion, involving the proliferation of insulin-expressing, glucose transporter 2-low (Ins+Glut2LO) progenitor cells." (PMID 34326390, 2021). "Summarizing, whereas the duration of the HFD may determine the consequence on skeletal muscle autophagy, the effect of insulin to attenuate autophagy is preserved in HFD-fed mice otherwise afflicted by peripheral insulin resistance." (PMID 34336862, 2021). "In pregnancy-induced diabetes, most patients are not insulin deficient, rather they have insulin resistance and high glucose levels." (PMID 35046934, 2021). "As such, changes in insulin signaling may affect brain plasticity and promote insulin resistance, for example." (PMID 34576151, 2021). "It is suggested that LCN2 may be a significant key to the pathogenesis of inflammation, leading to insulin resistance, followed by an increase in fasting plasma glucose and fasting plasma insulin." (PMID 34212049, 2021). "Surprisingly, different studies showed that T2D-associated SNPs impact more on insulin secretion rather than insulin resistance." (PMID 34681954, 2021). "Height, weight, body mass index (BMI), waist circumference, hip circumference, systolic blood pressure, fasting insulin, homeostasis model assessment of insulin resistance (HOMA-IR), uric acid and triglyceride were all positively associated with thyroid volume in the adolescents (P all < 0.001)." (PMID 34454459, 2021). "The pathogenesis of GDM includes insulin resistance and insufficient insulin secretion, but the specific mechanism remains unclear." (PMID 34404360, 2021). "In the long term, this mechanism provides an insight into how a high (in contrast to a low) glycemic index/load carbohydrate diet producing sustained high insulin secretion could contribute to the development of insulin resistance." (PMID 33419065, 2021). "Similarly, methyl cinnamate and its derivatives obtained by binding with phosphatidylcholine exhibited the properties of eliminating insulin resistance and restoring the correct cell response to insulin." (PMID 34684619, 2021). "Similarly, the results of other RCTs showed that cinnamon supplementation of the PCOS women resulted in a significant reduction of fasting glucose, insulin and insulin resistance, as measured by various indices and improvement of insulin sensitivity." (PMID 34627352, 2021).
Insulin resistance (continued). "Other placental hormones contribute to physiologic insulin resistance during normal pregnancies, but when the pancreatic compensatory insulin production is altered, as it is in GDM, they may end up contributing to GDM development." (PMID 34769262, 2021). "AP actions on histamine and muscarinic receptors have been shown to reduce acetylcholine-induced insulin secretion and result in the failure of leptin signaling, which may contribute to insulin resistance." (PMID 33776816, 2021). "Pueraria extract exerts an antidiabetic effect by activating a variety of mechanisms, such as reducing insulin resistance, increasing insulin release, inhibiting glucose absorption and reabsorption, and improving insulin sensitivity, glucose uptake, and metabolism." (PMID 34035828, 2021). "Previous studies have suggested that the insulin resistance observed in PCOS may be linked to aberrant adipose tissue morphology and function including enlarged adipocytes and decreased insulin-stimulated rates of glucose utilization in adipocytes." (PMID 33841184, 2021). "Additionally, metformin reduces insulin level, improves insulin resistance and exerts anti-inflammatory effects." (PMID 34356646, 2021). "Conversely, iron accumulation may contribute to insulin resistance and hyperinsulinemia by interfering with hepatic insulin extraction." (PMID 34124205, 2021). "While insulin resistance has been reported in offspring born to obese mothers as early as the newborn period, we did not observe any significant differences in the response of MatOb offspring to insulin stimulation during insulin tolerance testing." (PMID 34108935, 2021). "In T2D, impaired insulin signaling in peripheral tissues leads to insulin resistance." (PMID 33841321, 2021). "From the perspective of lipotoxicity, the accumulation of lipid intermediates like DAG and ceramides and the activation of PKC have been implicated in insulin resistance by triggering pathways that lead to serine phosphorylation of IRS-1, thereby suppressing insulin-stimulated glucose metabolism." (PMID 34580412, 2021). "In addition, excessive serum free fatty acids (FFA) can increase glycogen and basal insulin secretion and reduce liver insulin inactivation, resulting in hyperglycemia and insulin resistance." (PMID 33722242, 2021). "Similarly, kaempferol can inhibit the PI3K-Akt signaling pathway and increase insulin sensitivity and reduce insulin resistance." (PMID 34285700, 2021). "Insulin resistance appears to be a strong and independent risk factor for the development of asthma, but how insulin acts in the lungs and its local effects is not yet clear." (PMID 33520042, 2021). "Likewise, the insulin tolerance test (ITT) indicated insulin resistance was built up in the mice under high fat feeding." (PMID 34764881, 2021). "Postmenopausal decreases in ovarian hormones among older women result in increased low-density lipoprotein cholesterol (LDL-C) and triglyceride (TG), decreased high-density lipoprotein cholesterol (HDL-C), and increased insulin levels because of increased insulin resistance." (PMID 33918160, 2021). "We hypothesize mechanisms of IGFBP2 on the development of obesity and insulin resistance in an insulin-independent manner, which meant that could be evaluated as a therapeutic target." (PMID 33498859, 2021). "PI3K/mTOR pathway inhibition also affects insulin signaling, resulting in insulin resistance." (PMID 34830886, 2021). "Supplementation with carnosine or β-alanine may reduce fasting glucose, HbA1c, and HOMA-IR in humans and rodents, and fasting insulin in humans; both compounds show potential as therapeutics to improve glycemic control and insulin resistance." (PMID 34333586, 2021). "Triglyceride and WC are the important metabolic syndrome factors associated with insulin resistance, basal β-cell function and insulin levels in non-diabetic FDR men of Type 2 DM patients." (PMID 34134670, 2021).
Insulin resistance (continued). "Also, predominance change was discovered in insulin resistance based on the decline of fasting insulin level and HOMA-IR (p = 0.002 and <0.001 for fasting insulin and HOMA-IR, respectively)." (PMID 34368367, 2021). "Insulin resistance has been positively associated with BIP, MDD, SCZ, and cognitive defects, reflecting roles of insulin in energy metabolism and dopamine release in the central nervous system, contributing to memory and learning." (PMID 34211505, 2021). "Insulin resistance refers to the impaired response of targeted cells to insulin action." (PMID 34502295, 2021). "Overall, phytoestrogens, through their estrogen-like effects, may regulate glucose metabolism and insulin sensitivity and might contribute to the management of peripheral insulin resistance and its consequences." (PMID 34073781, 2021). "The addition of exogenous sodium butyrate could improve insulin sensitivity in HFD-induced insulin resistance mice by promoting mitochondrial function, peroxisome proliferator-activated receptorγcoactivator-1 (PGC-1) expression, and fatty acid oxidation." (PMID 34490132, 2021). "Moreover, PPARγ agonists reduce the inflammation mediators that promote insulin resistance and trigger an increase in circulating adiponectin levels with a positive outcome for insulin sensitivity and a decreasing effect on glucose production in the liver." (PMID 34827690, 2021). "This mitochondrial overload with acylcarnitines accumulation may then promote alterations in the phosphorylation status of insulin signaling intermediates as key mediators of the pathogenesis of skeletal muscle insulin resistance." (PMID 34959870, 2021). "We may speculate that SE FAE could have a beneficial effect in preventing atherosclerosis, insulin resistance and diabetes type 2, but this requires additional specific studies to confirm the possible insulin sensing effect of the SE fruits." (PMID 34834808, 2021). "Metformin is often described as an insulin stabilizer because, due to its positive effects on insulin acceptor and tyrosine kinase activity, it leads to a decrease in plasma insulin levels and insulin resistance." (PMID 35299877, 2021). "A recent randomized trial reported that probiotic consumption 8 × 109 vs. placebo, was related to a decrease in 4.8 points in the MDS-UPDRS score, along with a decrease in C-reactive protein, malondialdehyde and insulin levels; whereas insulin resistance improved and glutathione levels increased." (PMID 34566874, 2021). "Hyperinsulinemia and insulin resistance may mediate cancer progression via the insulin/insulin-like growth factor axis." (PMID 34684639, 2021). "VITD deficiency has a direct impact on the production and signaling of insulin pathways which may accelerate and contribute to the establishment of insulin resistance (IR)." (PMID 34578857, 2021). "The premise that insulin signaling could be therapeutic is strengthened by experimental studies investigating neurodegenerative diseases in models of insulin resistance." (PMID 33925119, 2021). "It is of interest that GLP-1 and adiponectin each retain microvascular vasodilatory actions in insulin resistant animals, suggesting that these agents may provide avenues for interventions to prevent microvascular insulin resistance." (PMID 34299190, 2021). "This suggests that carnosine might enhance insulin secretion from pancreatic β-cells, which may compensate for peripheral insulin resistance, leading to an improvement in glycemic control." (PMID 34333586, 2021). "The interaction of IDE with androgen and glucocorticoid receptors may be of relevance for steroid hormone action and metabolism, the crosstalk between insulin and steroid hormones, and the pathophysiology of glucocorticoid-mediated insulin resistance." (PMID 33477364, 2021).
Insulin resistance (continued). "Because the insulin tolerance test is a crude assessment of insulin sensitivity, additional testing using the gold standard hyperinsulinemic/euglycemic clamp is needed to confirm insulin resistance in the offspring." (PMID 35111136, 2021). "Based on these data, it is assumed that, when insulin resistance is present in a subject, glypican-4 levels may increase to enhance insulin sensitivity, if glypican-4 is acting as an insulin sensitivity-enhancing agent." (PMID 33740336, 2021). "Likewise, studies in human obesity and insulin resistance have revealed a clear relation between chronic administration of pro-inflammatory signaling pathways and decreased insulin sensitivity." (PMID 34294142, 2021). "Conversely, in DM a lack of insulin (as in T1DM) or insulin resistance (as in T2DM) creates a hyperglycemic environment causing metabolism to switch from an anabolic to a catabolic state." (PMID 33800470, 2021). "Insulin resistance is due to the impaired response of insulin-responsive cells, and lncRNA may regulate insulin signaling." (PMID 33478141, 2021). "Similarly, obese animals expressing the shiNOS vector to knockdown iNOS in the DVC presented with decreased food intake in response to DVC insulin treatment for 4 h, and their obese control littermates exhibited insulin resistance." (PMID 33227495, 2021). "In pig models, single nucleotide polymorphisms identified in the CCDC39 gene have been shown to be associated with body fatness, whereas reduced expression of the PDK gene (involved in glucose transport regulation by insulin) were observed in insulin-resistance obese subjects." (PMID 33975549, 2021). "Moreover, a recent mouse study demonstrated that chronic taurine supplementation further enhanced high-fat induced insulin resistance and suppressed the insulin secretion by pancreatic β cells." (PMID 33917297, 2021). "The role of IGFBP2 in glucose intake, insulin sensitivity, including insulin resistance, lipid profile, and obesity may contribute to metabolic syndrome." (PMID 33498859, 2021). "Resveratrol may improve insulin resistance, lower fasting blood glucose and insulin levels, and improve oxidative stress in patients with T2DM." (PMID 34484395, 2021). "The effect of insulin resistance on carbohydrate metabolism results in increased blood glucose concentration, and in physiological conditions insulin stimulates the entry of glucose into fat and muscle cells, and thus also affects glucose synthesis in the liver and kidneys." (PMID 33401397, 2021). "In OA patients with T2D, insulin resistance may develop not only in insulin-sensitive tissues such as muscle, liver or fat, but also in the synovial membrane." (PMID 33995414, 2021). "Overall, the average intra-similarity (pathways of the same types including “insulin signaling,” “insulin secretion and obesity,” and “insulin resistance and CVD” as illustrated above) in either CA-related or HM-enriched pathways was similar: higher SGDD score and lower SAE scores." (PMID 35003234, 2021). "We additionally estimated baseline insulin sensitivity and calculated insulin resistance by HOMA2." (PMID 34350730, 2021). "Likewise, the assessment of insulin sensitivity is clinically relevant, as persisting insulin resistance poses a significant challenge to the long-term health of survivors." (PMID 33709001, 2021). "Decreased maternal prepregnancy insulin sensitivity and preconception insulin resistance, impaired insulin response during the pregnancy, and insulin-producing β-cells dysfunction are believed to be the most important components of the pathophysiology of GDM development." (PMID 34212049, 2021). "Abnormalities of insulin signaling are responsible of insulin resistance." (PMID 32737757, 2021). "However, long-term systemic or intranasal administration of high-dose insulin can lead to insulin resistance, including the brain insulin resistance." (PMID 34769198, 2021).
Insulin resistance (continued). "Serum alanine aminotransferase, aspartate aminotransferase, gamma‐glutamyl transpeptidase, platelets, albumin, triglyceride, cholinesterase, fasting plasma insulin, homeostasis model of assessment of insulin resistance, and other markers have been used as indicators of liver conditions." (PMID 34463983, 2021). "Plasma amino acid alterations in the early stage of lifestyle-related diseases are due to obesity and insulin resistance-related inflammation, and these alterations are reversed by appropriate (nutritional, pharmaceutical, or surgical) interventions that improve insulin sensitivity." (PMID 35058883, 2021). "It was proposed that the impairment of this metabolic pathway may contribute to insulin resistance, leading to the accumulation of diabetogenic compounds which interfere with insulin action." (PMID 34681954, 2021). "Glucotoxicity and lipotoxicicty triggers oxidative and endoplasmic reticulum stress which stimulate the synthesis of inflammatory factors, further reducing the sensitivity of insulin target cells towards insulin, forming a vicious circle and aggravate insulin resistance." (PMID 34034759, 2021). "Insulin resistance is defined as a reduction in the metabolic response of insulin-responsive cells to insulin or an impaired/reduced response of blood glucose levels to circulating insulin at the systemic level." (PMID 34938205, 2021). "In a study after eight weeks of repeated ingestion of M. alba extract in KK-Ay mice, fasting plasma glucose (FPG) and insulin levels were measured and found an appreciable reduction in insulin resistance, and the onset time of urinary glucose excretion was delayed." (PMID 34220247, 2021). "Second, obesity is linked to insulin resistance, and the most crucial factor in modifying insulin sensitivity is the release of non-esterified fatty acids which diminish insulin receptor signaling." (PMID 33986312, 2021). "During insulin resistance, the secretion of the hormone from the pancreatic islet cells cannot trigger glucose uptake in metabolic tissues, leading to elevated blood glucose and insulin levels." (PMID 34299261, 2021). "Therefore, along with post-prandial glucose concentration, it is important to measure insulin concentration in order to evaluate a food's ability to reduce insulin resistance." (PMID 34395493, 2021). "Collectively, our above results suggested that hepatic GHR overexpression facilitated insulin resistance in skeletal muscle and white adipose tissue, which might be relevant to impaired systemic insulin signaling." (PMID 34373742, 2021). "While reports on glucose intolerance and insulin resistance were quite consistent, findings on body weight and adiposity as well as on blood levels of glucose, insulin, and/or triglycerides in 5HTT knock-out (5HTTKO) animals were rather inconsistent across studies." (PMID 34065591, 2021). "Insulin resistance of EAT adipocytes was evaluated by reactivity to insulin." (PMID 33440802, 2021). "Insulin resistance is defined as the tissues’ diminished response to insulin’s effects." (PMID 34575946, 2021). "Furthermore, the knockdown of HIF1 in adipocytes resulted in increased insulin secretion leading to increased glucose tolerance and amelioration of insulin resistance, establishing its potential as a promising T2DM therapeutic target." (PMID 34225729, 2021). "Insulin resistance is a pathological state in which target cells including hepatic cells, adipose cells and skeletal muscle cells are insensitive to the physiological level of insulin." (PMID 34414181, 2021). "This research showed that resveratrol may improve HOMA-IR and reduce HbA1c, fasting blood sugar, and fasting insulin levels, indicating that resveratrol may reduce insulin resistance, thereby lowering blood sugar and insulin levels." (PMID 34484395, 2021). "Sfrp5 is an adipokine which may play a protective role against obesity-related insulin resistance and T2D by binding to Wnt5a and improving insulin sensitivity." (PMID 34371968, 2021).